CRP (C-reactive protein)
Diseases named in the same sentence as CRP in open-access papers (continued):
Sharing a sentence is not in itself a finding about the gene and the disease.
Stroke (continued). "In 2023, a Meta-Analysis that involved nine studies with 3,893 participants showed the concentrations of peripheral CRP, especially in the acute stroke phase, are significantly increased for patients with cognitive decline after stroke compared to the patients without cognitive decline." (PMID 38414631, 2024). "However, in the Northern Manhattan Study of younger adults, higher serum CRP levels related to higher baseline disability, even when adjusting for baseline covariates, stroke, and myocardial infarction occurring during follow up." (PMID 38674833, 2024). "Multivariable analysis adjusting for confounders, including initial neurological severity, post-stroke acute infections, and C-reactive protein levels demonstrated that OR of poor functional outcome at three months increased according to the elevation of mean BT." (PMID 38206979, 2024). "One of the most important conclusions of the study was that copeptin, age, NIHSS score, infarct volume, stroke etiology, revascularization treatment, personal history of atrial fibrillation, CRP, homocysteine and cortisol levels are predictors of stroke recurrence." (PMID 39777314, 2024). "Based on these considerations, GPS can be used to predict stroke in endocarditis only if all different causes of CRP elevation and albumin reduction have been ruled out." (PMID 39292095, 2024). "In a study of 90,517 Chinese adults who had no stroke or myocardial infarction at baseline, they found that people with high levels of C-reactive protein had a 1.25 times higher risk of having a stroke than the normal population." (PMID 39247228, 2024). "The positive relationship between CRP gene expression and the number of days since stroke may allude to the fact that that inflammation is ongoing and has deleterious effects over time." (PMID 38802847, 2024). "CRP is the primary marker of proteins that are responsible for the response to inflammatory stimuli; hence, it is useful in the prediction of myocardial infarction and stroke." (PMID 38566084, 2024). "Multivariable analysis demonstrated that higher mean BT was significantly associated with less neurological improvement and neurological worsening, even after adjusting for initial neurological severity, post-stroke acute infections, and C-reactive protein levels." (PMID 38206979, 2024). "In addition, they demonstrated that copeptin has a higher predictive value for stroke recurrence than CRP, homocysteine, cortisol, or NIHSS score." (PMID 39777314, 2024). "An increasing body of research has reported a correlation between cognitive impairment following stroke and alterations in the production of biomarkers, including C-reactive protein (CRP), interleukin 6 (IL-6) and interleukin 10 (IL-10), which are found in blood, urine and other body fluids." (PMID 38984252, 2024). "Clinical trials further support the potential of RIPostC to enhance recovery in patients with stroke, as evidenced by improved NIHSS scores, reduced high-sensitivity (hs)-CRP levels, diminished brain tissue infarct volume, and enhanced cognitive function post-stroke." (PMID 38816852, 2024). "Importantly, our study demonstrates a positive correlation between systemic inflammatory markers, including WBC count, NE count, CRP level, and Hcy level, with stroke severity and adverse functional prognosis." (PMID 39238889, 2024). "Thus, stroke recovery in patients with only the relevant IL-6 polymorphism (rs1800795) may have additional risk insofar as differential IL-6 levels could functionally mimic CRP rs1130864 which increases CRP levels in Han Chinese populations and leads to worse outcomes." (PMID 38502340, 2024). "Increased LMP7 at admission was associated with decreased Th2 cells (P=0.014), elevated Th17 cells (P<0.001), C-reactive protein (P=0.005), National Institutes of Health Stroke Scale (NIHSS) score (P=0.007), and disease severity (defined by NIHSS score) (P=0.010)." (PMID 38404572, 2024).
Stroke (continued). "CRP had a significant mediating role in the association of METS-IR and UA with stroke risk." (PMID 39634177, 2024). "Interestingly, in patients with stroke and AF, proteins involved in the inflammatory response (CRP, LBP, and A1AG1) were significantly increased compared to those without AF, and TTR and RBP were significantly decreased." (PMID 38886511, 2024). "In conclusion, we constructed six risk prediction models for stroke recurrence in patients with AIS by machine learning algorithm (ML), introducing four independent risk factors associated with stroke recurrence (i.e., right hemisphere, HCY, CRP, and SS)." (PMID 37051146, 2023). "The outcomes showed an increased risk of stroke in patients with significative carotid artery disease, nonresponsive to therapy, monitored through a series of serum biomarkers (homocysteine, C-reactive protein, and oxidized LDL)." (PMID 36832132, 2023). "The relationship between CRP and recurrent stroke has been indicated in previous clinical research." (PMID 36836211, 2023). "Validation of our findings in a multicentric setting could pave the way for interventional studies exploring CRP apheresis as a possible tool to break this ischemia-inflammation cascade in stroke patients." (PMID 37360331, 2023). "The most important finding of the study, which will be valuable for clinicians in practice, is that MII can be a potent and independent index in determining stroke severity when compared to the previously used blood-related indices such as CRP and neutrophil count." (PMID 37577267, 2023). "However, as an acute-phase protein, CRP was correlated with brain damage, which was directly reflected by severity of stroke or TIA clinically." (PMID 36836211, 2023). "Moreover, the observation that most stroke patients showcase high-CRP levels is noteworthy given that activation of the secondary complement system and subsequent secondary brain damage through CRP has been shown experimentally." (PMID 37360331, 2023). "The coronary heart disease rate, atrial fibrillation rate, degree of carotid stenosis, white blood cell count, neutrophil percentage, apolipoprotein A1, NHR, NLR, and C-reactive protein (CRP) were higher in the moderate-to-severe stroke group than in the mild stroke group." (PMID 37327299, 2023). "This meta-analysis revealed the correlation between hs-CRP levels and the prognosis of patients with stroke, but results should be interpreted with caution, given the great heterogeneity across included studies with no single study found in the sensitivity analysis to reduce the heterogeneity." (PMID 37342777, 2023). "Moreover, earlier reports support the presence of high OS and hs‐CRP levels in stroke, cardiovascular and beta‐thalassemia patients." (PMID 36577716, 2023). "The finding that only when HRV was low, patients with right-sided stroke had significantly higher inflammation (CRP), than those with left-sided stroke, may be understood by the hemispheric differences in immunity." (PMID 37048532, 2023). "In this model, the predictive value of age, blood pressure, pulse pressure, history of hyperlipidemia, history of memory-related diseases, emotional, nervous, or psychiatric problems, low physical performance, hs-CRP, and TyG level on new stroke events are emphasized." (PMID 37388187, 2023). "Finally, a ratio of CRP and T3 levels indicated a 53.5% poor functional outcome and an 80.4% poor cognitive outcome in stroke patients at the time of discharge." (PMID 37606393, 2023). "A correlation between CRP and infarct size and severity of stroke per se has been described before." (PMID 36836211, 2023). "Elevated CRP levels can lead to increased mortality after stroke, which may be related to inflammation-induced endothelial cell dysfunction and platelet activation." (PMID 36908612, 2023). "Additionally, studies from Guangyao Wang and his team suggest a connection between Hs-CRP and poor outcomes one year after stroke." (PMID 37509012, 2023).
Stroke (continued). "Similarly, in the case of stroke, CRP levels are rapidly elevated, and this acute phase response occurs in the context of widespread inflammation, reflecting the low specificity of CRP elevation." (PMID 37485268, 2023). "Nine cohort studies with 3893 stroke patients were analyzed, which revealed that patients with higher CRP levels in the acute stage of ischemic stroke might have higher risks of CD." (PMID 37509012, 2023). "The association with incident stroke appeared to be driven by elevated CRP, as opposed to differences in wealth (high wealth/high CRP: HR 1.37, 95% C.I. 1.04; 1.81)." (PMID 37808231, 2023). "This suggests a potential link between increased CRP levels and cognitive decline post-stroke." (PMID 37509012, 2023). "The monomeric form of CRP was found to be colocalized with the angiogenetic marker endoglin (CD105) in stroke cases and found to stimulate ERK1/2 phosphorylation, resulting in cell migration and the creation of tube-like structures, regardless of the CD16 axis." (PMID 37873776, 2023). "Both stroke and SARS-CoV-2 infection cause elevation of CRP levels." (PMID 37260778, 2023). "Future research could incorporate alternative measures such as clinical assessments and independent ratings and explore the physiological effects of social support and hope on prognostic markers of stroke recovery, such as cortisol and C-reactive protein." (PMID 35966472, 2022). "The key finding from this study is that whilst CRP retained significant independent association with mortality in the subgroup of patients with previous stroke, IL-6 and VWF did not." (PMID 35042473, 2022). "Our study adds to the evidence that chronic low-grade inflammatory markers fibrinogen and CRP are related to the early occurrence of depressive symptoms within 2 weeks of stroke onset, and furthermore, plasma fibrinogen level at admission is an independent predictor of PSD at acute stage of stroke." (PMID 36009095, 2022). "Increased serum levels of D-dimer, fibrin degradation products, and CRP are more often seen in stroke with concomitant cancer, and the clot retrieved during thrombectomy has a more fibrin- and platelet-rich constitution compared with that of atherosclerotic etiology." (PMID 35785404, 2022). "Whether CRP apheresis is useful in atherosclerosis, myocarditis and dilated cardiomyopathy, neurological disorders and stroke, or even in autoimmune disease, requires further systematic investigation." (PMID 35407379, 2022). "Elevated levels of CRP after stroke have been related to poor functional outcome and mortality." (PMID 36010292, 2022). "We evaluated the association of elevated hs-CRP levels (≥ 3 mg/dL) and CVD events including myocardial infarction, ischemic heart disease, stroke, CVD, CVD mortality, and all-cause mortality in those with LDL-C ≥ or < 130 mg/dL Cox frailty models was used to determine possible interactions." (PMID 35614388, 2022). "The trend of more frequent infections, more frequent use of antibiotics, and higher blood CRP when compared to unstimulated patients should be associated with de facto more severe stroke rather than the use of stimulation." (PMID 35893412, 2022). "In addition to a TH2 shift, there are also increases in inflammatory factors, including IL-6 and CRP, following stroke." (PMID 38566903, 2022). "Since coronary atherosclerotic heart disease and atherosclerotic cerebral infarction share the similar vascular pathophysiology, CRP levels after stroke may also have prognostic value in clinic." (PMID 35659067, 2022). "Additionally another study found to an increase in plasma UA concentration isconnected with an elevated level of C-reactive protein, which is a significant biomarker of myocardial infarction, stroke, and vascular mortality." (PMID 37323554, 2022).
Stroke (continued). "Considering the clinically relevant factors including APACHE II score on ICU admission, mechanical ventilation, vasopressor, and hyperosmolar therapy, an early CRP level may help to predict in-hospital mortality of neurocritically ill patients with stroke." (PMID 36079002, 2022). "High levels of CRP on admission were positively correlated with worse functional status on discharge (measured using the Rankin and Barthel scales) and high mortality rates estimated 2.5 years after stroke." (PMID 35330458, 2022). "A confirmative cohort meta-analysis showed a linear association between CRP level and stroke (P = 0.940), as well as with CVD (P = 0.429), and CHD (P = 0.931); for each 1-mg/L increase in CRP level, the pooled RRs for stroke, CVD and CHD were 1.07, 1.18, and 1.12, respectively." (PMID 36185479, 2022). "In our study, both the values of RDW, N/L and CRP were significantly higher in stroke patients." (PMID 35471128, 2022). "Thirdly, although CRP has been linked to an increased risk of CVD, such as myocardial infarction, stroke and aortic valve stenosis, the authors did not assess the relationship between CRP and these CVDs in this study as this was beyond the scope of this work." (PMID 34478414, 2022). "The differences in research findings might be due to the differences of timing of PSD diagnosis, the diagnostic criteria for PSD, variability of source, measuring method and timing of CRP, and type of stroke." (PMID 36009095, 2022). "The LASSO regression analysis yielded seven variables that most strongly correlated with adverse prognosis after thrombolysis in AIS, including age, NIHSS score, history of atrial fibrillation, mechanical thrombectomy, blood CRP level, stroke classification, and syndecan-1 level." (PMID 35910391, 2022). "As for stroke, associated biomarkers were GDF-15, NT-proBNP and CRP." (PMID 34935094, 2022). "Interestingly, blood CRP levels differ between stroke subtypes, since large‐vessel strokes had higher CRP levels at follow‐up compared with all other stroke subtypes, including small‐vessel strokes, cardioembolic strokes, cryptogenic strokes, and others." (PMID 35971650, 2022). "In addition, compared to those with normal CRP levels, individuals with elevated-CRP levels had significantly higher risks of new-onset stroke in all models." (PMID 36262245, 2022). "However, the CRP level lost its significance when adjusted with other predictors such as female sex, stroke severity and fibrinogen level." (PMID 36009095, 2022). "It is therefore likely that the association with CRP could be due to more severe cases of SAP and higher stroke severity (which are more likely to cause disability) leading to higher levels of inflammatory makers." (PMID 31037709, 2021). "Serum CRP levels were compared between the two groups: non-stroke and acute stroke." (PMID 34135849, 2021). "Therefore, we aimed to perform a systematic review of published clinical studies assessing the effects of statins on CRP levels in patients with stroke." (PMID 34489618, 2021). "The present results further suggest that CRP is an independent risk factors for mortality (both short- and long-term) and that WBC level is associated with both stroke recurrence and dependency, adding new evidence for the role of CRP and WBC level in stroke prognosis." (PMID 33967939, 2021). "Crude models for END showed that age, previous antiplatelet, NIHSS, HT, OTT, PAO, stroke subtype, FBG, Hs-CRP, NLR, PLR, and LMR might be associated with post-thrombolysis END (P < 0.05)." (PMID 33610168, 2021). "CRP has also been reported to be correlated with stroke severity as measured by the NIHSS." (PMID 33532130, 2021). "The larger reductions in LDL‐C and other lipid targets, as well as CRP, may be more relevant for the inverse associations seen with CHD and total CVD than with stroke." (PMID 34346245, 2021).
Stroke (continued). "In conclusion, FGF-23 is likely signaling a worse health status in the FGF-23 upper-level group, since this group presented significantly more comorbidities (DM, CKD, previous MI and stroke) and more importantly, higher inflammation (higher CRP) and especially lower eGFR." (PMID 34297744, 2021). "We found participants with HGS weakness showed higher CRP level than those with normal HGS, which maybe a mechanism explaining the association weakness HGS with stroke prevalence and incidence." (PMID 33686964, 2021). "The median CRP level in patients with stroke affecting other vascular territories was 0.10 mg/dL." (PMID 34135849, 2021). "CRP is easily measured and commonly used and may be important in predicting functional prognosis after stroke." (PMID 34212039, 2021). "LPS levels correlate with CRP and LBP for all causes of stroke." (PMID 33753837, 2021). "Moreover, FC in stroke patients was positively correlated with CRP and negatively correlated with lymphocyte count and albumin." (PMID 35011900, 2021). "Elevated blood levels of inflammatory cytokines such as C-reactive protein (CRP), Interleukin-6 (IL-6), IL-18, IL-12, tumor necrosis factor-α, and C–C chemokine ligand 2 (CCL-2) were associated with poor outcome and increased mortality after stroke." (PMID 34336007, 2021). "Moreover, due to the evidence provided by these studies, and similar evidence investigating PSCI, it is fair to assume that high levels of serum CRP seen acutely post-stroke are likely predictors of the latter onset of PSD." (PMID 34884906, 2021). "Furthermore, we found the A allele (both in allele frequency and in homozygous genotype) to be more frequent among stroke patients who had CRP levels exceeding the cutoff 5 mg/L." (PMID 34680558, 2021). "Third, the inflammatory state illustrated by the elevation of CRP could induce a prothrombin state with consequent increased risks of arterial events such as stroke or venous thromboembolic events such as pulmonary embolism." (PMID 34506514, 2021). "Stroke patients initially displayed higher CRP levels than TIA and TGA patients." (PMID 34305782, 2021). "DN (HR, 1.56; 95% CI, 1.08–2.27; p = 0.019), HD introduction in late period (HR, 1.84; 95% CI, 1.06–3.21, p = 0.031), CRP > 0.3 (HR, 1.93; 95% CI, 1.35–2.76; p = 0.001) and URR < 65 (HR, 2.29; 95% CI, 1.57–3.32, p < 0.001) were also significant risk factors for stroke and/or death events." (PMID 34068165, 2021). "Elevated CRP may reflect the degree of stroke, tissue damage, or systemic inflammatory response to concurrent infection." (PMID 34212039, 2021). "C-reactive protein levels in the study population stratified by stroke status." (PMID 34135849, 2021). "This is further supported by a more recent study which showed that fatigue may be associated with systemic inflammation, based on correlations with the serum levels of IL-6 and CRP, in community-dwelling stroke survivors up to 5 months post-stroke." (PMID 34884906, 2021). "In the setting of an internal wound this generates a vicious cycle: The primary inflammation triggered by e.g., ischemia (e.g., acute myocardial infarction or stroke) activates a switch to anaerobic metabolism and a striking synthesis and secretion of CRP mediated by IL-6." (PMID 33679775, 2021). "Similarly, participants reporting these diseases had higher FeNO levels (except for stroke), and higher CRP levels (except for hypercholesterolemia)." (PMID 34123365, 2021). "Therefore, the significant level of inflammatory markers (such as D-dimer, CRP, and ferritin levels) confirms this pathway in stroke patients included in our study." (PMID 34461686, 2021). "It should be emphasized that CRP does not play a causal role in stroke, as indicated by large-scale evidence from Mendelian randomization studies." (PMID 32221345, 2020). "SDMA and CRP were only correlated at later time points at 3 days after stroke." (PMID 32150996, 2020).